ADAR (adenosine deaminase RNA specific)
Diseases named in the same sentence as ADAR in open-access papers (continued):
Sharing a sentence is not in itself a finding about the gene and the disease.
teratoma (1 paper, 2024). A non-seminomatous germ cell tumor characterized by the presence of various tissues which correspond to the different germinal layers (endoderm, mesoderm, and ectoderm). "As expected, ADAR exhibited ubiquitous expression across all teratoma cell-types, while ADARB2 was neural-specific and ADARB1 was most highly expressed in neural tissues, and at lower levels elsewhere." (PMID 39537590, 2024). "Our investigation commenced with an enrichment analysis of ADAR-KO teratomas, unveiling a pan-teratoma reduction in ADAR-expressing cells and discernible variations in cell type compositions across perturbations." (PMID 39537590, 2024). "To validate the observed increase in Adipogenic-MSCs within teratoma cells following ADAR-KO, we conducted experiments using primary human MSCs in vitro." (PMID 39537590, 2024). "Similar to week 10 teratomas, we observed ubiquitous expression of ADAR across all stages of teratoma development, while ADARB2 exhibited neural-specific expression, and ADARB1 showed strongest expression in neural tissues but also was expressed at low levels elsewhere." (PMID 39537590, 2024). "Notably, within Schwann Cell Progenitors (SCPs), ADARB1 (p-value = 4.13E-02, Cohen’s D = 1.73), in comparison to ADAR (p-value = 9.26E-02, Cohen’s D = 1.21), seemed to mostly contribute to the significant rise in SCP AEI (p-value = 1.56E-03, Cohen’s D = 2.01) throughout teratoma development." (PMID 39537590, 2024).
uterine tumors (1 paper, 2020). "Multiple deletion mutations in the mesoderm group (e.g., Deletion-3 prime UTR ADAR, BHLHE40, ZFX, etc.)mainly occur in the cases with uterine tumors." (PMID 33308219, 2020).
cancer (255 papers, 2010 to 2026). A tumor composed of atypical neoplastic, often pleomorphic cells that invade other tissues. "RNA editing, particularly A-to-I editing mediated by ADAR enzymes, has also been implicated in cancer." (PMID 40918643, 2025). "The second approach explores potential avenues for cancer treatment, utilizing endogenous-ADAR to correct driver mutations essential for tumor development and progression." (PMID 40330550, 2025). "Cancer therapeutics under development harness context-specific mechanisms to target tissues, cell/cancer type, and ADAR variant." (PMID 40362314, 2025). "In this study, we investigated the prospects of endogenous-ADAR to target inherited variants associated with cancer risk in pediatric syndromes and adults with high-penetrance disease, as well as treating cancer by correcting driver mutations in tumors." (PMID 40330550, 2025). "First, analyzing germline single nucleotide variants in cancer predisposition genes, we find that endogenous-ADAR can revert a fifth of them, reducing the risk of cancer development later in life." (PMID 40330550, 2025). "Out of the 566 putative cancer-risk SNVs suitable for endogenous-ADAR editing, 102 were detected as present at least once in gnomAD (with an average frequency of 1.82 × 10−5)." (PMID 40330550, 2025). "Tumor development, immune escape, and treatment resistance are all significantly impacted by the widespread RNA editing events caused by the dysregulation of ADAR activity in cancer." (PMID 40852728, 2025). "To evaluate the feasibility of this approach, we map the landscape of inherited cancer predisposition mutations and driver mutations that can be corrected via endogenous-ADAR across multiple cancer types." (PMID 40330550, 2025). "We first systematically studied the potential application scope of endogenous-ADAR editing to correct key mutations in childhood cancer predisposition syndromes, as well as high-penetrance germline mutations associated with cancer in adults." (PMID 40330550, 2025). "ADAR encodes an enzyme that catalyzes A-to-I editing in RNA and has been implicated in promoting cancer hallmarks in multiple cancer types, including breast, thyroid and gastric malignancies." (PMID 38773080, 2024). "Follow-up analyses estimated the roles of APOBEC/ADAR mutations and mRNA levels in mutational signatures among various cancer types, as adjusted for defects in DNA repair/replication (DRR) pathways." (PMID 38965255, 2024). "The adenosine deaminase acting on RNA (ADAR) enzymes was associated with the highly aggressive biologic behaviour and poor prognosis in many cancers." (PMID 37189448, 2023). "In total, 1153 positive genes associated with ADAR mRNA expression were obtained through cBioPortal for Cancer Genomics to construct an ADAR-related coexpression gene network." (PMID 36660243, 2023). "In summary, we demonstrated that ADAR is ubiquitously expressed across cancers and is associated with poor clinical outcomes in most cancers." (PMID 37414093, 2023). "We identified pathways enriched in ADAR and their related genes and explored the association between ADAR expression and the cancer immune microenvironment score and response to immunotherapy." (PMID 37414093, 2023). "Subsequently, we explored ADAR mutations, associated genes, and potential molecular pathways across cancers." (PMID 37414093, 2023). "ADAR editing is essential for survival in mammals, but its deregulation is also associated with cancer initiation and progression." (PMID 34496885, 2021). "Depletion of ADAR in numerous cancer cell lines causes reduced proliferation and increased apoptosis." (PMID 35586115, 2021). "Loss of ADAR in some cancer cell lines causes activation of the type I IFN pathway and the PKR translational repressor, leading to inhibition of proliferation and stimulation of cell death." (PMID 35586115, 2021).
cancer (continued). "Consistent with its proposed role in preventing dsRNA sensing, loss of ADAR in many human cancer cell lines leads to activation of the type I IFN pathway through activation of MAVS and translation repression by activation of PKR." (PMID 35586115, 2021). "We propose that engineered-guided-RNAs that bind ADAR and direct it to fix RNA mutations would bring new opportunities to identify cancer biomarkers at early stage." (PMID 33215051, 2020). "Adenosine-to-inosine (A-to-I) RNA editing is an essential post-transcriptional mechanism mediated by ADAR enzymes that have been recently associated with cancer." (PMID 30760294, 2019). "The rapid maturation of AID/APOBEC and ADAR deamination mutation signatures associated with a prediction of cancer progression was first shown by analyzing changes in the Inf‐DBDs of high‐grade serous ovarian (HGsOv) carcinoma." (PMID 30802996, 2019). "In summary, we found that ADAR expression is decreased in GBM, matching with the overall editing reduction in this cancer compared to the normal brain, with ADAR1 directly correlating with AEI and ADAR2 directly associated with REI values." (PMID 30760294, 2019). "It is also previously shown that RNA editing and ADAR expression are significantly altered in most cancer types and increased editing activity is associated with patient survival." (PMID 30911020, 2019). "For example, ADAR mainly targets Alu elements, and aberrant ADAR activity has been linked to a variety of cancers." (PMID 30774645, 2019). "Corroborating this idea, several studies have already established a clear precedent for ADAR activity being implicated in cancer biology." (PMID 30197877, 2018). "Previous studies have indicated that disturbed adenosine deaminase acting on RNA (ADAR) expression is able to alter mRNA and miRNA adenosine to inosine (A-to-I) levels associated with cancer pathogenesis." (PMID 25673044, 2015). "The ADAR proteins and RNA editing targets have been studied in many human diseases associated with RNA editing, including various cancers." (PMID 24509948, 2014). "In addition, aberrance in ADAR activity has been linked to human diseases such as cancer, metabolic diseases, viral infections, and autoimmune disorders." (PMID 40351534, 2025). "Different cancer types exhibit diverse distributions of mutation types, suggesting that the number of mutations correctable by endogenous-ADAR may vary among them." (PMID 40330550, 2025). "Complete resolution of germline mutations using endogenous-ADAR is still a distant goal, due to limited efficiency, but even partial correction might be beneficial in postponing the onset of cancer to a later age." (PMID 40330550, 2025). "This is a G > A missense variant that may serve as a good target for endogenous-ADAR in a variety of cancer types." (PMID 40330550, 2025). "Here, we systematically chart the scope of cancer mutations that endogenous-ADAR can correct." (PMID 40330550, 2025). "Yet, our findings portray a favorable and encouraging landscape of correctable mutations in cancer, pointing to the possibility of future leveraging the unique capabilities of endogenous-ADAR therapy towards clinical cancer risk/prevention and treatment outcomes." (PMID 40330550, 2025). "Furthermore, the contextual duality of ADAR functions across cancer types necessitates integrative diagnostic frameworks that combine RNA editing signatures, isoform expression profiles, and immune phenotyping." (PMID 40852728, 2025). "Recently, ADAR dysfunction has been implicated in cancer development." (PMID 38880983, 2024). "ADAR editing in cancer cells have been shown to associate with patients’ survival, affect cancer cell viability, and increase the diversity of cancer cell proteome." (PMID 37468903, 2023). "Furthermore, we evaluated the pan-cancer immune infiltration landscape and found that ADAR was associated with infiltrating immune cells." (PMID 37414093, 2023).
cancer (continued). "ADAR proteins are linked to different types of cancers thanks to their ability to generate inosines (see as examples); herein, we demonstrated that ADAR1, as an RNA-binding protein, is a powerful oncogene that inhibits cancer growth in vivo independently of its ability to generate inosines." (PMID 33509238, 2021). "The ADAR-mediated adenosine-to-inosine editing has also been linked to several types of cancers." (PMID 33996910, 2021). "ADAR with the ability to change DNA-encoded genetic information after transcription, could be an important contributor in cancer development." (PMID 32410589, 2020). "ADAR-mediated RNA editing is essential for survival in mammals, however, its dysregulation causes aberrant editing of its targets that may lead to cancer." (PMID 30585209, 2018). "Indeed, altered expression and/or activity of ADAR enzymes has been linked to a variety of conditions, including cardiovascular and neurological diseases and cancers." (PMID 27911851, 2016). "Moreover, ADAR expression is positively correlated with tumor mutation burden and microsatellite instability in a variety of cancers, indicating that ADAR could be used as a biomarker of immunotherapy." (PMID 37414093, 2023). "Dysregulation of ADAR activity or RNA editing has been associated with various diseases, including cancer, neurological disorders (such as epilepsy and amyotrophic lateral sclerosis), and autoimmune diseases, suggesting that ADARs may be recognized as potential therapeutic targets." (PMID 37612540, 2023). "Furthermore, ADAR is associated with the survival of patients with a variety of cancers." (PMID 37414093, 2023). "Aberrant adenosine-to-inosine (A-to-I) RNA editing, catalyzed by adenosine deaminase acting on double-stranded RNA (ADAR), has been implicated in various cancers, but the mechanisms by which microRNA (miRNA) editing contributes to cancer development are largely unknown." (PMID 36599932, 2023). "As ADAR-deficient cells are defective in DNA repair, it will be worth exploring if those tumors with overexpression or downregulation of these factors might benefit from specific DNA damage–inducing cancer treatments." (PMID 33996910, 2021). "Hence, the inconsistency in ADAR expression or activity may be a causative factor in a variety of diseases including cancer." (PMID 32410589, 2020). "Tudor-SN is a member of the RISC complex and also known as SND1, and it has been implicated in various cancers and has been shown to regulate miRNA processing and expression by degrading primary-miRNA transcripts that undergo adenosine deaminase acting on RNA (ADAR) editing." (PMID 26097876, 2015). "ADAR enzymes exhibit diverse, and sometimes opposing, functional roles across distinct cancer types, governed by both tumor-specific transcriptomic contexts and shared molecular pathways." (PMID 40852728, 2025). "To demonstrate its clinical relevance in the context of cancer, we highlight here three major well known cancer drivers that are suitable for endogenous-ADAR out of many such examples that are provided in the various tables in Results." (PMID 40330550, 2025). "Ten cancer types exhibited significantly higher editing potential by endogenous-ADAR, with the highest being pancreatic and liver." (PMID 40330550, 2025). "In cancer, dysregulation of ADAR activity contributes to tumorigenesis, immune evasion, and therapeutic resistance by editing key transcripts involved in critical biological processes." (PMID 40852728, 2025). "Surveys of human cancer-derived cell lines in vitro using RNA interference or gene editing approaches revealed that 11–80% are dependent on ADAR for survival with estimates varying by statistical method and tumor type." (PMID 40618019, 2025). "For many of the patients studied in PCAWG, covering multiple cancer types, endogenous-ADAR can potentially target at least one identified driver mutation." (PMID 40330550, 2025).
cancer (continued). "ADAR editing of miRNAs is one mechanism that links altered A-I editing to changes in gene expression and cancer cell growth." (PMID 40362314, 2025). "In a genome-wide CRISPR screen, many cancer cell lines derived from various tissues depended on ADAR for survival." (PMID 40141064, 2025). "Here, our objective is to explore systematically the potential of endogenous-ADAR for cancer prevention and treatment, considering its unique advantages and straightforward design for therapy." (PMID 40330550, 2025). "This precision oncology paradigm will inform ADAR-targeted strategies and reshape our understanding of RNA editing as a modifiable dimension of cancer immunobiology." (PMID 40852728, 2025). "By synthesizing recent findings from preclinical and clinical studies, we will elucidate how ADAR-mediated RNA editing contributes to cancer progression and shapes the immune landscape of tumors." (PMID 40852728, 2025). "Since the roles of ADARs vary depending on the type of cancer, the mechanisms of action of each ADAR should be clearly demonstrated and identified in each relevant cancer prior to the development of therapeutic strategies for ADARs." (PMID 38689093, 2024). "Collectively, these diverse functions of ADAR in miRNA regulation imply its high potential for application as a multifariously effective target in cancer treatment." (PMID 38689093, 2024). "Repressing cancer cell migration/invasion and reversing the carcinogenic process can be achieved by knocking out ADAR in LUAD cells." (PMID 38706740, 2024). "While the impact of APOBEC on human diseases and cancer has garnered significant attention due to its direct influence on DNA, research on ADAR-mediated RNA editing remains limited." (PMID 39000531, 2024). "Variations in specific malignant tumors make both A‐to‐I editing and ADAR enzymes viable candidates for specific biomarkers." (PMID 38706740, 2024). "Recent studies indicate widespread dysregulation of ADAR-mediated RNA editing across many immune-related diseases, such as human cancer." (PMID 38203521, 2023). "We first illustrated the mRNA expression of ADAR in normal versus cancer tissues in pan-cancer using the TCGA database." (PMID 37414093, 2023). "Analysis of the correlation between ADAR expression and immune infiltration of cancer revealed that ADAR was correlated with the number of immune cells in most tumors, with the most significant positive correlation with the infiltration of M1 macrophages." (PMID 37414093, 2023). "Altered ADAR expression or activity leads to abnormal editing patterns, which impact cancer-related processes." (PMID 37612540, 2023). "Analysis of both editomes showed that ADAR editing sites that have the potential to increase the proteome diversity are very rare in human cancer cells." (PMID 37468903, 2023). "First, by integrating information from multiple databases, we found that ADAR is abnormally upregulated in most cancers, including at the transcriptional and protein levels, and is associated with the malignancy and prognosis of a variety of cancers." (PMID 37414093, 2023). "Consistent with transcription levels, ADAR protein levels are significantly elevated in a variety of cancers." (PMID 37414093, 2023). "The results showed that ADAR expression was upregulated in most cancers but downregulated only in GBM, KICH, and SKCM." (PMID 37414093, 2023). "Recognizing that ADAR expression is upregulated in cancer, we further explored its potential role in cancer malignancy." (PMID 37414093, 2023). "ADAR enzyme-catalyzed A-to-I RNA editing has emerged as a major role in carcinogenesis and cancer progression." (PMID 37217462, 2023). "This shows the clinical value of ADAR as a response marker in the immunotherapy of these two cancers." (PMID 37414093, 2023). "Finding from single-gene GSEA of ADAR in pan-cancer further confirmed that ADAR participates in the immune signal pathway, especially the interferon pathway." (PMID 36660243, 2023).